PPP1R11 (protein phosphatase 1 regulatory inhibitor subunit 11)
Description:
Atypical E3 ubiquitin-protein ligase which ubiquitinates TLR2 at 'Lys-754' leading to its degradation by the proteasome. Plays a role in regulating inflammatory cytokine release and gram-positive bacterial clearance by functioning, in part, through the ubiquitination and degradation of TLR2. Inhibitor of protein phosphatase 1.
Synonyms: HCGV; TCTE5; Tctex5; HCG-V; CFAP255; IPP3
Tractability: PROTAC: UniProt records ubiquitination sites on it; ubiquitination databases record sites on it.
Gene: Protein-coding gene on chromosome 6 (30,066,709 to 30,070,333, forward strand). Ensembl gene ENSG00000204619.
Subcellular location (Human Protein Atlas): Vesicles
Gene Ontology:
Molecular function: phosphatase binding; protein binding; protein phosphatase inhibitor activity; ubiquitin protein ligase activity; protein phosphatase 1 binding; protein serine/threonine phosphatase inhibitor activity
Biological process: ubiquitin-dependent protein catabolic process; defense response to Gram-positive bacterium; negative regulation of cytokine production; protein ubiquitination
Cellular component: cytoplasm; nucleus
Genetic constraint (gnomAD): Loss-of-function variants: 10 observed, 11.82 expected, observed/expected ratio (o/e) 0.85, 90% interval 0.52 to 1.43. The upper end of that interval is the gene's LOEUF score, 1.43, which puts it in group 5 of 6, group 1 being the genes least tolerant of losing a copy. Missense variants: 114 observed, 184.67 expected, observed/expected ratio (o/e) 0.62, 90% interval 0.53 to 0.72. Synonymous variants: 56 observed, 62.49 expected, observed/expected ratio (o/e) 0.9, 90% interval 0.72 to 1.12.
Homologues: Orthologues: chimpanzee PPP1R11 (100% identical), macaque PPP1R11 (100% identical), pig PPP1R11 (98% identical), guinea pig PPP1R11 (97% identical), dog PPP1R11 (96% identical), rat Ppp1r11 (96% identical), mouse Ppp1r11 (89% identical), rabbit PPP1R11 (83% identical), zebrafish ppp1r11 (59% identical), tropical clawed frog ppp1r11 (54% identical), Drosophila melanogaster CG13994 (37% identical), Drosophila melanogaster I-3 (33% identical), and 1 more.
Diseases named in the same sentence as PPP1R11 in open-access papers:
PPP1R11 is named in the same sentence as 13 diseases in open-access papers, as found by Europe PMC text mining. Sharing a sentence is not in itself a finding about the gene and the disease. The quoted sentences say what the papers report.
acute lung injury (1 paper, 2016). A condition of lung damage that is characterized by bilateral pulmonary infiltrates (pulmonary edema) rich in neutrophils, and in the absence of clinical heart failure. "To investigate the in vivo relevance of the PPP1R11/TLR2 pathway, we assayed white blood cell (WBC) pellets for PPP1R11 and TLR2 expression in control and S. aureus-infected patients from our Acute Lung Injury Registry and Biospecimen Repository." (PMID 27805901, 2016).
HCMV infection (1 paper, 2024). "Our findings indicate that HCMV infection disrupts PP1 function through the temporal dysregulation of at least nine recognized regulatory subunits, PPP1R10, PPP1R7, YLPM1, PPP1R11, PPP1R9A, PPP1R8 (NIPP1), PPP1R9B, PPP1R12C, and URI1." (PMID 39772267, 2024).
Obesity (1 paper, 2025). Accumulation of substantial excess body fat. "For example, LRPPRC is involved in cytoskeletal regulation and bone development, PMAIP1 is associated with obesity, and PPP1R11 has roles in cell proliferation and fat metabolism." (PMID 40630222, 2025).
staphylococcus aureus infection (1 paper, 2016). An infectious process in which the bacteria Staphylococcus aureus is present. "There is a negative correlation between PPP1R11 and TLR2 levels in white blood cell samples isolated from patients with Staphylococcus aureus infections." (PMID 27805901, 2016).
infection (3 papers, 2014 to 2023). The state of being infected such as from the introduction of a foreign agent such as serum, vaccine, antigenic substance or organism. "The protein coding genes ZNRD1, RNF39 and PPP1R11, along with the ncRNA ZNRD1-AS1, have been associated with disease states that are related to autoimmunity, immunity, and infection; while EPM2A and SHPRH have been associated with glycogen metabolism, cancer, and chemical dependency." (PMID 25642351, 2014). "In addition, the analysis revealed that some of these proteins had been previously associated to SARS-CoV-2 early (FKBP2; UBXN1; PPP1R11), middle (UBXN1; PPP1R11; CAPN5) and late-stage infection in human male blood (FKBP2; UBXN1; PPP1R11; SURF4; SSU72)." (PMID 37063416, 2023).
immune diseases (1 paper, 2019). "Hence, targeting PPP1R11 instead of the PP1 catalytic core may be beneficial in eliciting specific immunotherapeutic outcomes in treatment of autoimmune and other immune diseases." (PMID 30882958, 2019).
inflammation (1 paper, 2016). Aberrant reaction of the microcirculation characterized by movement of fluid and leukocytes from the blood into extravascular tissues. "Lentiviral gene transfer or knockdown of PPP1R11 in mouse lungs significantly affects lung inflammation and the clearance of Staphylococcus aureus." (PMID 27805901, 2016).
tumor (1 paper, 2018). "Additionally, several non-receptor kinases and phosphatases such as PRKCD, PPP1R11, CRKL and PTPRA4 were identified for the first time as implicated in the crosstalk between CAFs and tumor epithelial cells." (PMID 29946230, 2018).
PPP1R11 also shares sentences with these, for which no sentence is quoted: colorectal cancer (2 papers); autoimmune disease (1); cancer (1); hepatocellular carcinoma (1); viral infections (1).